IFNG (interferon gamma)
Diseases named in the same sentence as IFNG in open-access papers (continued):
Sharing a sentence is not in itself a finding about the gene and the disease.
anemia (123 papers, 2008 to 2026). A reduction in the number of red blood cells, the amount of hemoglobin, and/or the volume of packed red blood cells. "Our data also identified IFNγ as the key driver of A20 deficient myeloproliferation, anemia and lymphopenia." (PMID 31477755, 2019). "In hamsters infected with L. donovani, anemia associated with lethal infection was correlated with increased apoptosis of erythroid progenitors and an increase of IFNγ in the BM and spleen." (PMID 30619317, 2018). "In contrast to these results obtained using adoptively transferred wild type CD4+ T cells, CD4+ T cells isolated from IFNγ-deficient B6.Ifnγ−/− mice we unable to induce anemia, despite equally efficient engraftment and activation." (PMID 30619317, 2018). "In summary, we have shown that IFNγ-producing CD4+ T cells contribute to anemia in a model of VL, via a mechanism that involves loss of both macrophages and mesenchymal stromal elements from the BM erythropoietic niche leading to dyserythropoiesis." (PMID 30619317, 2018). "Collectively, this study shows that NK-, NKT- and CD8-derived IFNγ is crucial for enhanced erythrophagocytosis by myeloid phagocytic cells and consequently for the induction of acute inflammation-associated anemia." (PMID 26070118, 2015). "Previously, we showed that IFNγ-production by these cells induces PU.1 in hematopoietic progenitors, which chronically impairs erythropoiesis in the bone marrow and causes severe anemia over time." (PMID 23975731, 2013). "Prior studies support a causal relationship between interferon gamma and worsening anemia." (PMID 35309862, 2022). "Results indicate that IFNγ plays a crucial role in the recruitment and activation of erythrophagocytic myeloid cells, as mice lacking the IFNγ receptor were partially protected against trypanosomosis-associated inflammation and acute anemia." (PMID 26070118, 2015). "Collectively, this study shows that NK, NKT and CD8+ T cell-derived IFNγ is a critical mediator in trypanosomosis-associated pathology, driving enhanced erythrophagocytosis by myeloid phagocytic cells and the induction of acute inflammation-associated anemia." (PMID 26070118, 2015). "Infiltration of parasitized cells in bone marrow crowds out progenitor cells and shift the cytokine environment by favoring production of inflammatory cytokines, such as TNF and IFNγ, that inhibit erythropoiesis, which can result in anemia." (PMID 39514579, 2024). "As we observed previously, aIFNg appeared most effective in preventing anemia and reducing serum IFNg levels, and it did so when administered alone or along with ruxolitinib." (PMID 37228616, 2023). "aIFNg, administered alone or with ruxolitinib, is most effective at reversing anemia and reducing serum IFNg levels." (PMID 37228616, 2023). "S. Typhimurium infections were shown to result in anemia and lead to the development of hemophagocytic macrophages, related to IFNG and IL-12-induced iron efflux from tissues." (PMID 30200471, 2018). "As IFNγR-/- mice did not suffer as much from the acute anemia observed in wild type C57BL/6 mice, we examined the contribution of each IFNγ producing cell subset to acute anemia induction and systemic IFNγ levels." (PMID 26070118, 2015). "At the time of anemia induction at day 6 post infection, both spleen and liver had equal amounts of IFNγ producing cells (approximately 3.7 x 106)." (PMID 26070118, 2015). "Interestingly, inhibition of IFNγ has been shown to be effective in reducing several of the pathologies associated with hyperinflammation in CpG-induced MAS, including splenomegaly, anaemia, thrombocytopenia and hypercytokinaemia." (PMID 38775430, 2024). "Another potential adverse effect noted within this study was the action of interferon gamma in the setting of thalassemia, as demonstrated by a participant with β‐thalassemia who developed worsening anemia that resolved after discontinuation of interferon gamma‐1b." (PMID 35309862, 2022).
anemia (continued). "Human fHLH has been modeled in PRF1 deficient mice infected with LCMV, and both CD8 T cells and interferon-gamma (IFNγ), a cytokine known to be the main driver of anemia in models of fHLH and fulminant MAS, were found to be critically important mediators of mouse mortality." (PMID 30774631, 2019). "Interferon gamma and IL-1 also seem to act directly by inhibiting the growth of pro-erythrogenic cells and apoptosis of erythroid precursors, thus contributing to the development of anemia in these patients." (PMID 27737630, 2016). "The data presented in this paper show that in the absence of IFNγ, mice are protected from infection-associated acute anemia." (PMID 26070118, 2015). "The other hypothesis for anemia secondary to infection is linked to effects of various cytokine mediators of inflammation, such as tumor necrosis factor (TNF), interleukin (IL-1 and IL-6), and the interferons (IFNs)-IFNγ." (PMID 38042804, 2023). "Anemia due to a chronic disease, such as cancer, results from the dysregulation of iron homeostasis induced by inflammatory cytokines such as interleukin-6 (IL-6) and interferon gamma (IFN-γ) as well as the suppression of erythropoietic activity, and it associates with poor OS among cancer patients." (PMID 38049762, 2023). "However, in many patients enhanced formation of pro-inflammatory cytokines including interleukin 1 (IL-1), tumor necrosis factor alpha (TNF-α) or interferon gamma (IFN-γ) leads to the development of functional iron deficiency (ID) and anemia of chronic disease (ACD)." (PMID 34458328, 2021). "In addition, infection-associated alteration of RBC membranes is independent of IFNγ and its contribution to acute inflammation-associated anemia development seems to be minor." (PMID 26070118, 2015). "Moreover, anemia in children with solid tumours was related to IFNγ and TNFα." (PMID 20204172, 2009). "TNF could have a crucial impact on anemia through its capacity to modulate the activation, growth and the phagocytic potential of macrophages involved in antibody independent erythrophagocytosis, a process which is dependent on IFNγ." (PMID 18688274, 2008). "Em infection elicits production of interferon gamma (IFNγ) and modulates the hematopoietic stem cell (HSC) niche contributing to profound anemia and thrombocytopenia observed upon infection." (PMID 39229265, 2024). "For example, in Trypanosoma brucei infection, anemia is in part caused by nitric oxide (NO) production, and pro-inflammatory cytokines, such as IFNγ and TNF positively correlate with anemia severity." (PMID 30619317, 2018). "This IFNγ is derived consecutively by NK, NKT and CD8+ T cells, hence these cells all play a crucial role in the induction of inflammation and anemia." (PMID 26070118, 2015). "In addition, Tc1 cells (IFNγ-producing CD8+ T cells) promote dysfunction of hematopoietic stem cell and depletion of myeloid lineage progenitor cells, resulting in anemia." (PMID 31772580, 2019). "However, the chronic and excessive production of IFNG or repetitive supplementation with downstream cytokines (e.g. IL15) induces cell exhaustion, bone marrow failure, accompanied by anemia." (PMID 32905461, 2019). "Collectively, these data support the conclusion that both the medullary changes in erythropoiesis and peripheral anemia seen in experimental VL arise as a consequence of CD4+ T cell activation and IFNγ production, independently of any potential contributions from splenomegaly." (PMID 30619317, 2018). "In the absence of infections, the prolonged infusion of IFNG led to the appearance of hemophagocytic macrophages and the subsequent development of anemia." (PMID 30200471, 2018). "Unlike with IFNγ depletion, these mice still developed profound anemia following LCMV infection." (PMID 36969228, 2023).
anemia (continued). "It is interesting to mention that IFNγ-/- mice die within 20 days of infection, in contrast to wild type mice, which die around day 35 post infection, which could indicate that the protection against acute anemia is of no clinical significance." (PMID 26070118, 2015). "Infection of nu/nu mice, lacking both CD4 and CD8 T cells, resulted in a diminished anemia phenotype compared to C57BL/6 mice, and coincided with reduced levels of IFNγ in serum and spleen cell culture." (PMID 26070118, 2015). "Neutralization of IFNγ in LCMV-infected Prf1-/- mice, but interestingly not MCMV-infected mice, has been shown to prolong their survival, concomitant with resolution of anemia." (PMID 36969228, 2023).
Hypertension (123 papers, 2011 to 2026). The presence of chronic increased pressure in the systemic arterial system. "Activated T cells are able to secrete cytokines, such as tumor necrosis factor-alpha (TNF-α) and interferon-gamma (IFN-γ), which have been linked to kidney damage and hypertension in pre-clinical models." (PMID 37375602, 2023). "However, the product of IFNγ and TNFα positively associated with NCB in models adjusted for age, sex, hypertension, hyperlipidaemia, waist: hip ratio, statin use as well as individual IFNγ and TNFα levels (β = 0.28, p < 0.001)." (PMID 32646751, 2020). "Following the elevation of Th cells in the kidneys of F. alocis-treated mice, cytokines produced by T cells, including interleukin-17A (IL17A), interferon-gamma (IFNγ), and tumor necrosis factor alpha (TNFα), play crucial roles in hypertension." (PMID 40396735, 2025). "Interferon-gamma (IFNγ), renowned for its diverse roles in immune regulation, extends its influence beyond traditional immunity, impacting the development of hypertension and contributing significantly to T2D pathogenesis." (PMID 40868889, 2025). "Our animal data revealed that F. alocis aggravated hypertension and induced renal infiltration of IFNγ+ T cells." (PMID 40396735, 2025). "CTLs, through the FASL-FAS system, induce apoptosis in target cells, and their production of cytokines like interferon-gamma (IFNγ) and tumor necrosis factor (TNF) has been linked to hypertension and renal damage in mice models." (PMID 38606081, 2024). "It is known that γδT lymphocytes synthesize molecules with a confirmed role in vascular wall fibrosis and thus in the development of hypertension such as IL-17, IFNγ, TNFα, or CCL5." (PMID 39195289, 2024). "In contrast, significantly more patients in the “high IFNG” cohort suffered from arterial hypertension (57% vs. 20%) and renal insufficiency (14% vs. 4%) compared to the “low IFNG” cluster." (PMID 38892346, 2024). "Sh2b3 deficient mice also exhibited enhanced T-cell activation with increased IFNγ production in hypertension." (PMID 36951464, 2023). "These mice also exhibited increased splenic and renal T-cell IFNγ production with hypertension induction and in response to IL-12 stimulation." (PMID 36951464, 2023). "Hypertension increases the T cell populations and inflammatory cytokine secretion of tumor necrosis factor TNFα, IFNγ, and IL-17A." (PMID 36839596, 2023). "The activated T cells produce interferon-gamma (IFN-γ), interleukin 17A (IL-17A) and tumor necrosis factor-alpha (TNF-α) which causes vascular damage and lead to hypertension." (PMID 37342440, 2023). "The “interferon gamma signaling” pathway modulates immune responses as well as influences hypertension." (PMID 36685671, 2023). "Excess dietary salt alters the gut microbiota and activates dendritic cells that in turn activates T cells and stimulate production of interleukin 17 (IL-17), tumor necrosis factor alpha (TNF-α) and interferon gamma (IFN-γ) leading to hypertension." (PMID 35469059, 2022). "In particular, interferon-gamma (IFN-γ) and interleukin-17 (IL-17) produced by activated T lymphocytes contribute to hypertension by inducing oxidative stress injury and endothelial dysfunction." (PMID 36703963, 2022). "Animal studies demonstrated that F. alocis might aggravate hypertension by promoting infiltration of IFNγ+ T cells in the kidney." (PMID 40396735, 2025). "Given the co-existence of significant elevation in blood pressure and IFNγ in T2D patients, it is important to investigate whether IFNγ is the “culprit” that contributes to the high prevalence of hypertension among T2D." (PMID 40868889, 2025). "F. alocis may aggravate hypertension via the accumulation of IFNγ+ T cells, at least in part, in the kidneys." (PMID 40396735, 2025). "Thus, in this study, the high IFNG AD group showed a higher average age, suffered more frequently from arterial hypertension and had an upregulation of the pathway for cardiovascular disease." (PMID 38892346, 2024).
Hypertension (continued). "Prolonged hypertension leads to the systemic release of cytokines, including interleukin 17, interferon gamma, tumor necrosis factor-α, and interleukin 6, which contribute to renal fibrosis, alter sodium membrane transportation, and increase oxidative stress and arterial stiffness." (PMID 37842465, 2023). "These cells have a low activation threshold, produce TNFα and IFNγ and may contribute to vascular dysfunction and hypertension, which is recorded both during the COVID-19 disease and directly after vaccination." (PMID 38137381, 2023). "Moreover, PGE2 has been found to stimulate IFNγ receptor expression on human lymphocytes, further implicating IFNγ signaling mechanisms in inflammation and hypertension." (PMID 36970367, 2023). "In CD4+ and CD8+ T cells, IFNγ secretion was higher in SARS-CoV-2 patients with hypertension." (PMID 36839596, 2023). "Collectively these data evidence the critical role of IFNγ in mediating immune-driven hypertension." (PMID 36970367, 2023). "IFNγ and IL-17, especially, have been confirmed to be elevated in clinical hypertension." (PMID 36970367, 2023). "A potential mechanism by which CD4+ cells contribute to hypertension is that these cells secrete inflammatory cytokines IFNγ and Interleukin-17 (IL-17), as mice deficient in these cytokines failed to secrete these cytokines and develop hypertension in response to ANG II infusion." (PMID 36160839, 2022). "However, hypertension-related IFNγ production by either NK cells or T cells could possibly explain the low expression of endothelial nNOS in brains of hypertensive animals seen in our study." (PMID 25519173, 2014). "Within hypertension, these γδ T cells as well as CD4+ T cells function by aiding in the activation of CD8+ T cells or through cytokine production, including IFNγ and IL-17A." (PMID 36970367, 2023). "We further found the cytokine IFNγ was critical for this infiltration to take place in the DOCA + Salt model and adoptive transfer models of hypertension." (PMID 36970367, 2023). "Increased numbers of central memory CD8+ T cells, activated CD8+ T cells producing Interferon-gamma (IFNγ) and tumor necrosis factor (TNF), and TH17 cells have been reported in patients with hypertension." (PMID 35743626, 2022). "The hypertension could alter the cytokine profile as we observed that these 9 patients differed from other MDs by CTACK, IP10, MIG, IFNγ, and IL4 levels." (PMID 36175465, 2022). "Neither IFNγ (β = 0.01, p = 0.71) nor TNFα (β = 0.07, p = 0.06) reached statistical significance in their individual associations with NCB (fully adjusted model included age, sex, hypertension, hyperlipidaemia, waist: hip ratio and statin use)." (PMID 32646751, 2020). "Moreover, our research indicates that IFNγ acts as a hypertensive factor by facilitating the formation of immunological synapses between CD8+ T cells and renal tubular cells, leading to increased sodium retention and hypertension in a classic salt-sensitive hypertension model." (PMID 40868889, 2025). "Within MD group, patients with hypertension had significantly higher levels of CTACK, IP10, MIG, IFNγ, and IL4 than these without hypertension (independent sample t-test)." (PMID 36175465, 2022).
experimental autoimmune encephalomyelitis (110 papers, 2005 to 2026). An autoimmune demyelinating disease of the central nervous system that is produced experimentally in animals by the injection of homogenized brain or spinal cord in Freund's adjuvant. "IFNγ can stabilize brain endothelial tight junctions and prevent infiltration of leukocytes into the brain in experimental autoimmune encephalomyelitis, but conversely causes BBB leakage during reovirus infection." (PMID 33391257, 2020). "In rats, direct injection of IFNγγinto the brain caused demyelination, whereas systemic administration of IFNγ protected against demyelination in animals with experimental autoimmune encephalomyelitis." (PMID 33391257, 2020). "Th17 cells and interferon-gamma (IFNγ)-producing Th1 cells are implicated in induction of MS and its animal model experimental autoimmune encephalomyelitis (EAE)." (PMID 25071447, 2014). "Their results revealed that IFNγ-Exos significantly reduced demyelination and neuroinflammation while enhancing motor skills in experimental autoimmune encephalomyelitis mice." (PMID 41328354, 2026). "To further elucidate the role of astrocytic IFNγ signaling on the PD-1/PD-L1 axis in vivo, we induced the experimental autoimmune encephalomyelitis (EAE) model of MS in Aldh1l1-CreERT2, Ifngr1fl/fl mice." (PMID 37828609, 2023). "It has been shown that IFNγ and GM-CSF, which are increased in PV patients, can guide the transition of monocytes into Mdcs in experimental autoimmune encephalomyelitis, a model of tissue inflammation." (PMID 37095207, 2023). "Autoreactive CD4+ T cells, including IFNγ-secreting T helper (Th) 1, IFNγ/IL‐17-secreting Th17, or IFNγ/GM‐CSF-secreting cells, play an important role in MS, which is supported by data from the experimental autoimmune encephalomyelitis (EAE) mouse models." (PMID 35488271, 2022). "EVs from IFNγ pre-activated human BM-MSCs reduced experimental autoimmune encephalomyelitis (EAE) via the generation of Treg cells." (PMID 34685707, 2021). "Similar to our findings, a significant down-regulation in the expression levels of IFNG gene in cultured mononuclear cells of experimental autoimmune encephalomyelitis mice, fed with sesame oil, has been found." (PMID 33578642, 2021). "Genetic ablation of IFNγ aggravates the disease course in experimental autoimmune encephalomyelitis (EAE), a well-established animal model of MS." (PMID 33297574, 2020). "Nevertheless, modest ER stress induced by IFNγ in mature oligodendrocytes of adult mice protected against experimental autoimmune encephalomyelitis-induced demyelination, axonal damage, and oligodendrocyte loss." (PMID 23173607, 2012). "Experimental autoimmune encephalomyelitis (EAE) was induced in transgenic mice expressing signaling defective dominant-negative interferon gamma (IFN-γ) receptors on astrocytes to determine the influence of inflammation on astrocyte activity." (PMID 22848713, 2012). "As just one example, the cytokine interferon-γ (IFNγ) exacerbates multiple sclerosis in humans and in the corresponding rat model (experimental autoimmune encephalomyelitis)." (PMID 20333307, 2010). "In contrast, IFNγ has a protective effect in the mouse experimental autoimmune encephalomyelitis model." (PMID 20333307, 2010). "In situ hybridization analysis of LPS/IFNg and experimental autoimmune encephalomyelitis (EAE)–induced CNS inflammation revealed that only a subset of CNS macrophages express Golli-MBP." (PMID 17982583, 2007). "Conversely, Th17 cells differentiate without TGF-β, express T-bet and produce IFNγ, adopting an inflammatory phenotype associated with Experimental Autoimmune Encephalomyelitis." (PMID 40195474, 2025). "In experimental autoimmune encephalomyelitis (EAE; a mouse model of autoimmune-driven neuroinflammation), Sirt7 deficiency causes inflammatory stress because of diminished peripheral interferon-gamma (IFN-γ) production and failed accumulation of regulatory T cells in the central nervous system." (PMID 37676263, 2024).